ATG2B (autophagy related 2B)
Diseases named in the same sentence as ATG2B in open-access papers (continued):
Sharing a sentence is not in itself a finding about the gene and the disease.
Sepsis (1 paper, 2025). Sepsis is defined as life-threatening organ dysfunction caused by a dysregulated host response to infection. "We believe that our findings are important in understanding the potential target of miR-143/ATG2B in sepsis-associated small intestinal barrier damage and will lead to further research in this area." (PMID 40773487, 2025). "GHS may improve small intestinal barrier damage in sepsis through miR-143/ATG2B-mediated autophagy, indicating miR-143/ATG2B was an underlying therapeutic target for sepsis." (PMID 40773487, 2025). "Moreover, miR-143 overexpression exacerbated barrier injury, reduced ATG2B level, and inhibited autophagy in the small intestines of septic rats, confirming the prominent roles of miR-143/ATG2B-mediated autophagy in sepsis-associated small intestinal barrier damage." (PMID 40773487, 2025). "This study found that GHS could improve small intestinal barrier damage in sepsis by promoting miR-143/ATG2B-mediated autophagy." (PMID 40773487, 2025). "Although the regulation of GHS on autophagy has been proved by both animal and cellular experiments, it remains uncertain whether GHS improves small intestinal barrier damage in sepsis by promoting miR-143/ATG2B-mediated autophagy." (PMID 40773487, 2025). "In conclusion, this research found that GHS had an improved effect on small intestinal mucosal barrier damage in sepsis, which may be achieved by promoting miR-143/ATG2B-mediated autophagy." (PMID 40773487, 2025). "Consistently, in vitro, GHS enhanced the viability and autophagy of LPS-stimulated IEC-6 cells, whereas miR-143 overexpression partially reversed these effects, which suggested that GHS may improve small intestinal mucosal barrier damage in sepsis by promoting miR-143/ATG2B-mediated autophagy." (PMID 40773487, 2025). "Thus, it is speculated that modulation of miR-143/ATG2B-mediated autophagy may be an effective strategy to ameliorate intestinal barrier damage in sepsis." (PMID 40773487, 2025). "Thus, miR-143/ATG2B-mediated autophagy plays a key role in intestinal barrier damage in sepsis." (PMID 40773487, 2025).
steatosis (1 paper, 2023). Increased lipid within the cytoplasm of cells. "In our study, Rg1 focused on ATG2B drastically inhibited lipid droplet formation in steatosis HepG2 cells, suggesting that Rg1 should be a doable therapeutic agent for the remedy of NASH." (PMID 36759837, 2023).
Stroke (1 paper, 2023). Sudden impairment of blood flow to a part of the brain due to occlusion or rupture of an artery to the brain. "The remaining autophagy-related genes, such as ATG12, ATG16L2, ATG2B, and BECN1 were also significantly increased in CE strokes while not all types of strokes." (PMID 37305740, 2023).
cancer (22 papers, 2014 to 2024). A tumor composed of atypical neoplastic, often pleomorphic cells that invade other tissues. "We showed that SNX29 expression was associated with most genes in most cancers, such as ATG2B, EPG, AMBRA1, and BECN1, in most cancers." (PMID 36829159, 2023). "Deregulating autophagy by the frameshift mutations of Atg2B, Atg5, Atg9B and Atg12 is involved in cancer development." (PMID 34829743, 2021). "Aberrant levels and mutations of ATG2B, which is involved in autophagosome formation and LDs morphology, are found in several cancers." (PMID 34845203, 2021). "Moreover, frequent mutations in the ATG2B gene were also reported in other cancers." (PMID 33488952, 2020). "Based on our results, the inhibition of autophagy promoted the development of cancer cells and affected chemosensitivity through suppressing ATG2B expression." (PMID 35992821, 2022). "Based on the Cancer Cell Line Encyclopedia, ATG2B expression seemed lower in CRC cells compared to other human cancer cell lines." (PMID 35992821, 2022). "Curcumin has been shown to upregulate the expression of autophagy‐related proteins, including ATG5 and ATG2B and induce overall autophagy flux in human cancers." (PMID 35029026, 2022). "ATG2B (Autophagy-Related Protein 2 Homolog B) is involved in autophagy, a key pathway mediating stress-induced adaptation and cellular damage control, which is exploited by cancer cells to survive starvation and hypoxia." (PMID 34274969, 2021). "Numerous studies have shown that other ATG genes, including ATG2B, ATG5, ATG9B, ATG12, and ATG16L1, are also associated with human different cancers." (PMID 34443541, 2021). "We further investigated the effect of ATG2B suppression in CCD-18Co cells on the proliferation of co-existing cancer cells." (PMID 34593902, 2021). "A number of studies on the ATG genes relevance to human cancers showed that other ATG genes are also oncogenically associated, including ATG2B, ATG5, ATG9B, ATG12 and ATG16L1." (PMID 31969156, 2020). "Some autophagy-related genes (ATGs), such as ATG2B, ATG5, ATG9B, and ATG12, have been reported to contain frameshift mutations in cancer, implicating the potential contributions to tumorigenesis and cancer metastasis." (PMID 38338839, 2024). "Although the function of autophagy was complex and often contradictory in cancers, but there were many evidences supporting that upregulation of ATG2B, ATG10, DAPK1 might contribute to good prognosis by promoting autophagy and apoptosis in ES." (PMID 35902797, 2022). "The mutations with mononucleotide repeats have been found in ATG2B, ATG5, ATG9B, and ATG12 genes in gastric and colorectal cancers, which may be involved in cancer development by dysregulating autophagy." (PMID 34443541, 2021). "ATG2B, ATG2A, ULK1, and RB1CC1 had a wide range of mutation frequencies in the pan-cancer analysis." (PMID 34636718, 2021). "The frameshift mutations with mononucleotide repeats have been found in ATG2B, ATG5, ATG9B and ATG12 genes in gastric cancer and colorectal cancer, which may be involved in cancer development by deregulating the autophagy process." (PMID 31969156, 2020).
cancer (continued). "Moreover, it has been shown that miR-130a, through its inhibitory effect on ATG2B and DICER1, inhibits the survival of cancer cells in CLL." (PMID 38473390, 2024). "Furthermore, treatment with curcumin led to attenuation of cancer stemness in TNBC CSCs; the expression of ATG5 and ATG2B was enhanced and there was an increase of autophagy flux." (PMID 35029026, 2022).
tumor (11 papers, 2014 to 2025). "Thus, although the ATG2B variant might influence tumour cell survival and/or chemotherapy responsiveness, it is unlikely to be an oncogenic driver." (PMID 34274969, 2021). "HOTAIR down-regulates Mir-130a-3p and reduces its binding to its target gene ATG2B, thereby affecting tumor chemosensitivity." (PMID 36924407, 2023). "The present report demonstrates a novel and important function of miR-4534 as a regulator of autophagy via suppression of ATG2B in the tumor stroma during colorectal tumorigenesis." (PMID 34593902, 2021). "Based on TIMER databases, a positive correlation was discovered between ATG2B and tumor-infiltrating lymphocytes, suggesting that ATG2B might influence the immunotherapy of CRC modulating the tumor-infiltrating immune cells, but functional studies of ATG2B still need further verification." (PMID 35992821, 2022). "Additionally, circDHX8 can competitively bind to RNF5, inhibiting the interaction between ATG2B and RNF5 to maintain the stability of ATG2B protein, thus promoting autophagy and tumor development in GC." (PMID 39901896, 2025). "The results revealed that ATG2B mRNA expression at each stage in tumor tissues was significantly different from those in noncancerous tissues of the subjects (P < 1.00×10-4)." (PMID 35992821, 2022). "To further explore the relationships between clinical variables and mRNA expression of ATG2B in CRC tissues, we chose the characteristics of tumor stages, metastasis, sex, age, family history, tumor site, BMI, and KRAS mutation status for analysis in TCGA datasets." (PMID 35992821, 2022). "ATG2B was lower-expressed in tumor tissues than in noncancerous tissues of the subjects TCGA database, P < 1.00×10-3; TCGA paired data, P < 1.00×10-3; GSE87211, P < 1.00×10-3 and in-house RNA-Seq data, P = 1.10×10-2." (PMID 35992821, 2022). "Comparing to normal group, ATG2B, ATG10, DAPK1 were all high expressed in tumor and cell lines." (PMID 35902797, 2022).
infection (4 papers, 2012 to 2021). The state of being infected such as from the introduction of a foreign agent such as serum, vaccine, antigenic substance or organism. "Differential induction of Atg2B protein production may therefore contribute to diverse regulations of autophagy upon infection and metabolic stress." (PMID 26771516, 2016). "Only modest changes were seen in the core autophagy machinery following infection, with the most notable effects being differential phosphorylation of FIP200 (RBCC1), ATG2B, and VPS15/p150 (PI3R4)." (PMID 34085925, 2021). "In addition, other autophagy-related proteins—Atg2b, Atg4b, and Dynll1—also showed similar expression patterns, suggesting that membrane recruitment of proteins to the autophagosome may be important for the DC response to infection." (PMID 32041786, 2020).
ATG2B also shares sentences with these, for which no sentence is quoted: knee osteoarthritis (2 papers); nasopharyngeal carcinoma (2); acute myeloid leukemia (1); cutaneous squamous cell carcinoma (1); deep vein thrombosis (1); gastrointestinal stromal tumor (1); glioma (1); head and neck squamous cell carcinoma (1); Insulin resistance (1); laryngeal squamous cell carcinoma (1); multiple myeloma (1); oral carcinoma (1); pharyngeal squamous cell carcinoma (1); rectal adenocarcinoma (1); tuberculosis (1).